IGLV3-10 (immunoglobulin lambda variable 3-10)
Description:
V region of the variable domain of immunoglobulin light chains that participates in the antigen recognition. Immunoglobulins, also known as antibodies, are membrane-bound or secreted glycoproteins produced by B lymphocytes. In the recognition phase of humoral immunity, the membrane-bound immunoglobulins serve as receptors which, upon binding of a specific antigen, trigger the clonal expansion and differentiation of B lymphocytes into immunoglobulins-secreting plasma cells. Secreted immunoglobulins mediate the effector phase of humoral immunity, which results in the elimination of bound antigens. The antigen binding site is formed by the variable domain of one heavy chain, together with that of its associated light chain. Thus, each immunoglobulin has two antigen binding sites with remarkable affinity for a particular antigen. The variable domains are assembled by a process called V-(D)-J rearrangement and can then be subjected to somatic hypermutations which, after exposure to antigen and selection, allow affinity maturation for a particular antigen.
Synonyms: IGLV310; V2-7
Gene: Immunoglobulin variable (V) gene on chromosome 22 (22,811,747 to 22,812,281, forward strand). Ensembl gene ENSG00000211669.
Subcellular location: Secreted; Cell membrane
Gene Ontology:
Biological process: immune response
Cellular component: extracellular region; immunoglobulin complex; plasma membrane
Homologues: Orthologues: macaque IGLV3-10 (79% identical), tropical clawed frog igl (55% identical). Paralogues in human: IGLV3-25 (86% identical), IGLV3-16 (84% identical), IGLV3-27 (82% identical), IGLV3-1 (77% identical), IGLV3-22 (71% identical), IGLV3-9 (71% identical), IGLV3-19 (70% identical), IGLV3-21 (69% identical), IGLV3-12 (66% identical), IGLV3-32 (63% identical), IGLV6-57 (59% identical), IGLV1-40 (58% identical), and 81 more.
Diseases named in the same sentence as IGLV3-10 in open-access papers:
IGLV3-10 is named in the same sentence as 2 diseases in open-access papers, as found by Europe PMC text mining. Sharing a sentence is not in itself a finding about the gene and the disease. The quoted sentences say what the papers report.
breast carcinoma (1 paper, 2024). "The findings of this study suggest that the combination of PON3, IGLV3‐10, and IGHV3‐73 proteins in a model demonstrates a significant ability to differentiate between individuals with breast cancer and HC." (PMID 39641443, 2024). "We used the XGBoost machine learning model and AUC value to screen out the optimal combinations of variables for breast cancer diagnosis from a variety of differential proteins: PON3, IGLV3‐10, and IGHV3‐73." (PMID 39641443, 2024).
IGLV3-10 also shares sentences with these, for which no sentence is quoted: COVID-19 (1 paper).